IL25 (interleukin 25)
Diseases named in the same sentence as IL25 in open-access papers (continued):
Sharing a sentence is not in itself a finding about the gene and the disease.
asthma (continued). "In children with asthma, TSLP, IL-25 and IL-33 are recognized as key epithelial mediators that define the T2-high endotype and have been highlighted as potential therapeutic targets and biomarkers of disease activity." (PMID 40981017, 2025). "In typical Th2‐high phenotype asthma, airway epithelium interacts with environmental factors to induce innate and adaptive immune and inflammatory responses, releasing TSLP, IL‐33, and IL‐25." (PMID 39800672, 2025). "It is clearly that the epithelial and epidermal derived alarmins IL-25, IL-33, and TSLP play crucial roles in the action of allergic inflammation in asthma and AD." (PMID 40236701, 2025). "During the course of both diseases, IL-25, IL-33, and TSLP cytokines are notably increased, which are all substantial in provoking a pathological immunologic response, proven in a mouse asthma model, and TSLP alone in a mouse AD model." (PMID 40149608, 2025). "Administration of anti-IL-25 antibodies in mice with ovalbumin or HDM and adenoviral Smad2 overexpression-induced asthma significantly decreased the Th2 immune responses and attenuated AHR and airway tissue remodeling." (PMID 41409758, 2025). "And the administration of IL-25 has been shown to induce lung eosinophilia and airway hyperreactivity (AHR), underscoring its critical role in the pathogenesis of asthma." (PMID 40236701, 2025). "Elevated levels of TSLP, IL-25, IL-33 and the IL-33 receptor serum stimulation-2 (ST2) in the serum and bronchial tissue of patients with asthma have also been found to correlate with T2 inflammation and disease severity." (PMID 38453256, 2024). "Thus, given that IL-17A and IL-25, which both use, in part, IL-17RA to exert their biological effects, are significantly greater in sputum of obese as compared to non-obese asthmatics, future studies focusing on the effectiveness of brodalumab in obese asthma is warranted." (PMID 38878250, 2024). "Furthermore, viral specificity should not be ignored due to RV has a robust association with asthma, and IL-25 may support RV replication." (PMID 39261649, 2024). "They empress pattern recognition receptors that detect the stimuli and secrete “alarmin cytokines” including IL-25, IL-33 and TSLP, which contributes to the pathogenesis of asthma." (PMID 38641850, 2024). "The type 2 inflammation in asthma is initiated by ‘alarmin cytokines’ such as TSLP, IL-25, and IL-33 secreted by BECs when sensitized by allergens." (PMID 38641850, 2024). "Sputum IL-25 is greater in obese as compared to lean asthmatics while BAL IL-33 and TSLP are greater in obese as compared to lean mice with experimental asthma." (PMID 38878250, 2024). "Our finding that montelukast increased IL25, IL33, and TSLP expression supports the reduced effectiveness of LTRAs in terms of the clinical outcomes of asthma." (PMID 36674744, 2023). "There are three epithelial cell-derived cytokines such as IL-25, TSLP, and IL-33 known to mediate Th2 inflammation and IL-33 has been identified to initiate type 2 responses in asthma in response to the clinically relevant allergens including HDM." (PMID 37237381, 2023). "IL-25, IL-33, and TSLP were identified as the principal regulators of type 2 immunity in patients with allergic disease and asthma in recent years." (PMID 36674744, 2023). "SA ILC2s demonstrated a 100‐fold increased release of IL‐6 following stimulation with IL‐2, IL‐33, IL‐25 and TSLP compared to mild asthma and the controls." (PMID 37114915, 2023). "In contrast with blockage alone, the combined blockade of IL-25, IL-33, and TSLP has been shown to further inhibit airway remodeling and inflammation in a mouse model of asthma." (PMID 38082335, 2023). "We investigated the effect of BT on the epithelial expression of the trio of alarmins IL-25 and IL-33 and TSLP which are well documented in asthma as well as on hBD2, an antimicrobial peptide." (PMID 37996952, 2023).
asthma (continued). "The epithelium-derived cytokines interleukin (IL)-25, IL-33, and thymic stromal lymphopoietin (TSLP) are important mediators that initiate innate type 2 immune responses in asthma." (PMID 36674744, 2023). "Mediators, which are derived from epithelial cells of the airways (AECs), include cytokine alarmins such as IL-25, IL-33, and thymic stromal lymphopoietin (TSLP), which have arisen as crucial elements in the pathogenesis of asthma." (PMID 37685567, 2023). "The researchers found that DEP-induced IL-25, IL-33, and TSLP expression was increased in primary bronchial epithelial cells from patients with mild asthma through the aryl hydrocarbon receptor and increased levels of acetyl-histone H3." (PMID 36674744, 2023). "have identified intelectin (ITLN) knockdown suppressed expression of IL-33, IL-25, and TSLP expression in asthma and atopic dermatitis models." (PMID 37153553, 2023). "Although the role of omentin in dengue is not known, omentin (intelectin) was shown to induce allergen induced production of IL-25, IL-33 and TSLP in asthma and atopic dermatitis." (PMID 37676889, 2023). "We also evaluated by qRT-PCR the effect of BT on the expression of IL-25, IL-33, TSLP and hBD2; typical asthma-related alarmins or antimicrobial peptides in BECs." (PMID 37996952, 2023). "It targets alarmins, which are key epithelial inflammatory cytokines involved in the pathogenesis of asthma, and is a novel group of antibodies (TSLP, IL-25, and IL-33)." (PMID 38203353, 2023). "That’s to say, p38 MAPK is vital for allergen induced epithelial production of IL-25 and thymic stromal lymphopoietin (TSLP), further mediating the type-2 allergic response in asthma." (PMID 35656293, 2022). "We also studied epithelial-cell-derived IL-33, IL-25, and TSLP, which were regarded as alarmins and played pivotal roles in the initiation of allergic inflammation in asthma." (PMID 35983066, 2022). "Epithelial cell-derived mediators including the alarmin cytokines IL-25, IL-33, and thymic stromal lymphopoietin (TSLP) have emerged as key players in propagating asthma pathogenesis." (PMID 35406669, 2022). "To explore the relationship among the levels of IL-4, IL-25, and S100A12 in nasal lavage fluid in patients with AR, asthma, and asthma comorbid AR, we performed Spearman correlation coefficient tests." (PMID 35348596, 2022). "Consistently, we detected IL-4, IL-5, IL-13, IL-25, IL-10, IL-33, and TSLP in induced sputum of asthma and proved a positive correlation between BIRC3 and these cytokines." (PMID 35287655, 2022). "Airway epithelial cells produce IL-33, IL-25, and thymic stromal lymphopoietin (TSLP) under allergen stimulation in the type 2 immune reaction of asthma." (PMID 36578010, 2022). "In summary, blockade of IL-25 during RV-A1 infection upregulated IFN gene and protein expression independently of viral load in ALI-differentiated BECS from donors with asthma." (PMID 35508632, 2022). "Airway epithelial cytokines IL-25, IL-33, and TSLP play important roles in the innate immune response to allergens and promote Th2 immune responses in asthma." (PMID 35126350, 2021). "In a mouse model of asthma, natural killer T cells (NKT) with a phenotype of CD4+IL-17RB+ are able to produce IL-13 and Th2 chemokines in response to IL-25 stimulation and therefore promote airway hyperresponsiveness." (PMID 34122457, 2021). "The airway epithelium is usually the first line of defense that is exposed to inhaled allergens and pathogens, releasing alarmins (including IL-25, IL-33, and TSLP) to propagate the development and exacerbation of asthma." (PMID 35126350, 2021). "Overall, epithelial miR-206 upregulates airway IL-25 and TSLP expression by targeting the CD39–extracellular ATP axis, which represents a potentially novel therapeutic target in type 2–high asthma." (PMID 33945508, 2021). "Airway ATP levels were increased and strongly correlated with elevated IL-25 and TSLP expression in type 2–high asthma patients." (PMID 33945508, 2021).
asthma (continued). "Airway ATP levels were markedly elevated and strongly correlated with IL-25 and TSLP expression in asthma patients." (PMID 33945508, 2021). "We observed a marked increase in the levels of epithelial cell–derived cytokines Tgf-β1, Tslp, IL-25, and IL-33 in BALF of allergen-induced mouse models of asthma." (PMID 34101619, 2021). "To date, there have been few head-to-head studies of IL-25, IL-33, and TSLP expression in human asthma." (PMID 33945508, 2021). "Airway miR-206 antagonism before HDM challenge suppressed IL-25, IL-33, and Tslp expression; ILC2 expansion; type 2 cytokine expression; and the cardinal features of asthma in mice." (PMID 33945508, 2021). "Of note, BALF ATP levels were strongly correlated with airway IL-25 and TSLP expression in asthma patients." (PMID 33945508, 2021). "Type 2–high asthma patients had higher miR-206 expression, lower epithelial CD39 expression, elevated BALF ATP levels, and higher epithelial IL-25 and TSLP expression than type 2–low asthma patients." (PMID 33945508, 2021). "In conclusion, epithelial miR-206 regulates airway IL-25 and TSLP expression and type 2 inflammation in asthma by targeting the CD39–extracellular ATP axis." (PMID 33945508, 2021). "We found that miR-206, the most highly expressed miRNA in type 2–high asthma relative to type 2–low asthma, targets the CD39–extracelluar ATP axis to regulate IL-25 and TSLP expression in cultured bronchial epithelial cells." (PMID 33945508, 2021). "Our data on airway IL-25, IL-33, and TSLP expression in asthma patients provide evidence for the potentially novel therapies targeting these cytokines in China." (PMID 33945508, 2021). "The epithelial cell–derived cytokines IL-25, IL-33, and thymic stromal lymphopoietin (TSLP) initiate type 2 inflammation in allergic diseases, including asthma." (PMID 33945508, 2021). "In order to write this narrative review, a literature search was carried out using the PubMed database, and as search words, we chose ‘asthma’, ‘alarmins’, ‘TSLP’, ‘IL-33′, ‘IL-25′, ‘anti-alarmins’, and ‘tezepelumab’." (PMID 34572294, 2021). "Epithelial IL25 transcript levels and BALF IL-25 protein levels were significantly higher in type 2–high asthma patients than in type 2–low asthma patients and controls." (PMID 33945508, 2021). "All these data support the critical role of IL-25, IL-33, and TSLP in asthma pathogenesis and type 2-driven inflammation." (PMID 34608100, 2021). "Current knowledge suggests that airway epithelial damage triggered by viral infections promotes the production of IL-25, IL-33, and thymic stromal lymphopoietin (TSLP), which in turn leads to the activation of ILC2 and exacerbation of asthma." (PMID 32823491, 2020). "The anti-IL-25 antibody significantly reduced the levels of IgE, IL-5, and IL-13; goblet cell hyperplasia; and eosinophil infiltration, and prevented AHR in murine asthma models." (PMID 31284537, 2019). "In murine models the intelectin transcript plays a key role in the expression of IL-25, IL23 and has been found to amplify type 2 immune response in asthma and atrophic dermatitis conditions in humans." (PMID 29703268, 2018). "In a murine model of RV-induced asthma exacerbation using OVA, lung levels of IL-25, expressed by epithelial cells and infiltrating immune cells are greatest in mice exposed to both OVA and RV." (PMID 29915592, 2018). "Positive feedback between IGF-1 and Th2 cytokines has been documented in asthma, as IGF-1 is inducible by repetitive intranasal challenge with IL-25 or IL-33 in murine asthma models." (PMID 30018981, 2018). "Release of epithelial cytokines, IL-33, IL-25, and TSLP, is the initial process during asthma exacerbation." (PMID 29977243, 2018). "Type-2 innate lymphoid cells (ILC2s) respond to the cytokines of thymic stromal lymphopoietin (TSLP), interleukin (IL)-25 and IL-33, thus contributing to airway diseases such as CRS and asthma." (PMID 28199345, 2017).
asthma (continued). "Given that IL-25 can induce a population of lung ILC2 with IL-17-producing ability, the potential role of this special ILC2 subset in the pathology of asthma in humans needs to be studied in the future." (PMID 29354125, 2017). "In this study, in order to investigate the correlation among IL-25, IL-5, IL-13 and nuocyte activities, we used OVA-sensitization and -challenging to induce the mouse model of asthma." (PMID 27617447, 2016). "Recently it has been claimed that each of a variety of cytokines, including IL-4, IL-17A, and IL-25, are essential drivers of rhinoviral induced exacerbation effects in OVA mouse models of asthma." (PMID 26879906, 2016). "Results show that the expression of IL-25 in both mRNA and protein exposed to OVA were much higher in the asthma groups than in other groups." (PMID 27617447, 2016). "Nevertheless, the potential of anti-IL-25 and anti-IL-33 therapeutics to suppress multiple components of the TH2 response responsible for asthma pathogenesis warrants more attention." (PMID 27378934, 2016). "Thus, blocking IL-25 may attenuate vascular remodelling and improve outcomes in asthma patients." (PMID 25889697, 2015). "IL-25, IL-33 and/or TSLP were increased in specimens from patients with asthma and in inflamed skin lesions of patients with atopic dermatitis." (PMID 26230091, 2015). "Subsequent studies have shown increased levels of IL-25, IL-33, and TSLP in patients with asthma that all have the potential to active ILC2." (PMID 24876829, 2013). "ILC2 are activated both by epithelial-derived cytokines such as IL-25, IL-33, and TSLP as well as leukotrienes found elevated in asthma, and yet ILC2 also produce amphiregulin, an important tissue repair mediator." (PMID 24876829, 2013). "IL-25, IL-33 and TSLP are also epithelial-derived cytokine that are important in the pathogenesis of CRSwNP and asthma, and may be potential relevant biomarkers for CRSwNP." (PMID 40469214, 2025). "In another study by Palacionyte and collaborators, researchers did not observe significant differences in IL-25 levels in T2-high asthma patients after 25 weeks of mepolizumab therapy." (PMID 40723867, 2025). "Moreover, another anti-IL-25 monoclonal antibody, XKH001, has been evaluated as therapeutic agents in clinical trials for asthma." (PMID 40236701, 2025). "The study conducted on people whose omentin expression in lungs was suppressed using nonsense mRNA showed that the synthesis of IL-25, IL-33, and TSLP was consequently decreased, directly linking omentin’s role in their production and, therefore, in the asthma development." (PMID 40149608, 2025). "This is similarly confirmed by this study, where the IL25 gene expression failed to be reliably detected in epithelial cells isolated from healthy individuals and patients with asthma." (PMID 40507979, 2025). "The importance of the alarmins, to include TSLP, IL-25 and IL-33, is that they are constitutively expressed by epithelial cells, and once released, activate Th2 cells and ILC2 responses in multiple allergic conditions and asthma." (PMID 40821845, 2025). "Moreover, a disrupted airway epithelium drives inflammation in asthma, promoting AHR through the secretion of alarmin cytokines such as thymic stromal lymphopoietin (TSLP), IL-25, and IL-33." (PMID 39199248, 2024). "Mediators including alarmins (IL-25, IL-33, TSLP) and OX40L have overlap between T2 and non-T2 inflammation and may signify unique pathways of asthma inflammation." (PMID 39194521, 2024). "No biologics targeting IL-25 or its receptor are approved or known to be in late-stage development for the treatment of asthma." (PMID 38609094, 2024). "Alarmins such as IL-25, IL-33 and TSLP function at the initial stages of the allergy cascade and are anticipated to have a more comprehensive impact on airway inflammation, potentially offer more effective asthma management than currently therapies." (PMID 39717777, 2024).
asthma (continued). "Mast cells play a key role in asthma pathophysiology and airway remodelling through the release of a plethora of cytokines (e.g. TSLP, IL-33, IL-25, IL-4, IL-13 and TGF-β) and angiogenic factors (e.g. VEGF-A), as well as other inflammatory mediators and bronchoconstrictors." (PMID 38609094, 2024). "In a murine model of asthma, protease allergens—such as papain and house dust mites (HDM)—and Aspergillus fumigatus damaged airway epithelial cells, releasing epithelial-derived cytokines such as IL-25, IL-33, and TSLP." (PMID 37371472, 2023). "Epithelium-derived cytokines, including interleukin (IL)-25, IL-33, and thymic stromal lymphopoietin (TSLP), are major immune mediators secreted by epithelial cells that contribute to type 2 immune responses and the development of asthma." (PMID 36674744, 2023). "The expression of IL-12, IL-23 and IL-25 in sputum was analyzed in a cohort of severe asthma and subjects with eosinophilic or non-eosinophilic asthma." (PMID 37898756, 2023). "In this study, we demonstrated that IL-25 protein levels were decreased in sputum from a cohort of nonsmoker severe asthma in the U-BIOPRED study." (PMID 37898756, 2023). "In the present study, we demonstrated that IL-25 expression was decreased in sputum from subjects with severe asthma, sputum cells from subjects with non-eosinophilic asthma, and in a mouse model of neutrophilia-dominant airway inflammation." (PMID 37898756, 2023). "ILC2s produce a large amount of IL-5 and IL-13 in response to epithelial-cell-derived cytokines, such as IL-25, IL-33, and thymic stromal lymphopoietin (TSLP), which are considered to play an essential role in the pathogenesis of allergic disorders, including asthma." (PMID 37371472, 2023). "In conclusion, through the NF-κB and MAPK pathways and histone modification, LTRAs increased IL25, IL33, and TSLP mRNA expression in lung and bronchial epithelial cells, which might provide support for the decreased effectiveness of LTRAs in asthma therapy." (PMID 36674744, 2023). "Of note, IL-25 expression in sputum were decreased in subjects with severe asthma or non-eosinophilic asthma." (PMID 37898756, 2023). "Studies indicate that IL-25, like IL-33 and TSLP, has a prime position in promoting T2 asthma." (PMID 36311787, 2022). "Studies have shown that IL-25 derived from epithelial cells can activate ILC2s and promote the production of type 2 cytokines in OVA-induced asthma models, suggesting that IL-25 may play a key role in the development of asthma." (PMID 35744915, 2022). "Although IL33- and IL25-induced iNKT cell activation has been shown to play an essential role in a mouse model of asthma, it remains unclear whether CD1d-restricted NKT cells stimulated by IL33 and IL25 contribute to AD progression." (PMID 36119077, 2022). "Hasegawa and colleagues have recently shown that serum levels of IL-17A were significantly different between uncontrolled and well-controlled patients, and that IL-17A levels were correlated with levels of IL-4, IL-25, IL-10, and IFN-γ in patients with uncontrolled asthma." (PMID 35546400, 2022). "The expression of IL-33, IL-25, and TSLP should be higher in ABPA and asthma theoretically." (PMID 35983066, 2022). "Using an in vivo mouse model of airway inflammation, we showed that Il25-/- mice displayed mitigated inflammatory responses and Th2 responses in HDM-induced asthma model, which was consistent with the previous OVA-induced studies or anti-IL-25 administrated mice model." (PMID 35615348, 2022). "In line with plasma IL-4 and IL-25 data, patients with asthma comorbid AR had higher levels of IL-5 (6.94 [5.74, 10.69]) than those without asthma (4.07 pg/ml [3.61, 4.72] pg/ml, P < 0.001)." (PMID 35348596, 2022). "Having confirmed that IL-25 was expressed in ALI-differentiated BECs and increased by RV-A1 infection, we next examined if IL-25 was modulating epithelial cell innate anti-viral immunity in a subset (n = 6) of BEC from donors with moderate-severe asthma." (PMID 35508632, 2022).